NSDHL (NAD(P) dependent 3-beta-hydroxysteroid dehydrogenase NSDHL)
Description:
Catalyzes the NAD(P)(+)-dependent oxidative decarboxylation of the C4 methyl groups of 4-alpha-carboxysterols in post-squalene cholesterol biosynthesis (By similarity). Also plays a role in the regulation of the endocytic trafficking of EGFR (By similarity).
Synonyms: H105E3; XAP104; SDR31E1
Tractability: Small molecule: a structure with a bound ligand is known; it belongs to a druggable protein family. Antibody: UniProt predicts a signal peptide or a membrane-spanning region. PROTAC: ubiquitination databases record sites on it; its protein half-life has been measured.
Gene: Protein-coding gene on chromosome X (152,830,967 to 152,869,729, forward strand). Ensembl gene ENSG00000147383.
Subcellular location: Endoplasmic reticulum membrane; Lipid droplet
Subcellular location (Human Protein Atlas): Endoplasmic reticulum; Lipid droplets
Pathways (Reactome):
Metabolism: Cholesterol biosynthesis via desmosterol (Bloch pathway); Zymostenol biosynthesis via lathosterol (Kandutsch-Russell pathway)
Gene Ontology:
Molecular function: 3-beta-hydroxysteroid dehydrogenase [NAD(P)+]/C4-decarboxylase activity; protein binding; 3-beta-hydroxy-Delta5-steroid dehydrogenase (NAD+) activity; 3-beta-hydroxysteroid dehydrogenase (NAD+)/C4-decarboxylase activity; oxidoreductase activity, acting on the CH-OH group of donors, NAD or NADP as acceptor
Biological process: cholesterol biosynthetic process; cholesterol metabolic process; steroid biosynthetic process; zymosterol biosynthetic process
Cellular component: endoplasmic reticulum; endoplasmic reticulum membrane; lipid droplet
Gene-disease validity (ClinGen):
ClinGen rates the evidence that NSDHL causes each of these diseases.
CK syndrome (X-linked): Moderate.
Homologues: Orthologues: chimpanzee NSDHL (99% identical), macaque NSDHL (97% identical), rabbit NSDHL (87% identical), dog NSDHL (86% identical), mouse Nsdhl (83% identical), pig NSDHL (83% identical), rat Nsdhl (82% identical), guinea pig NSDHL (79% identical), tropical clawed frog nsdhl (62% identical), zebrafish nsdhl (62% identical), Caenorhabditis elegans hsd-3 (22% identical), Caenorhabditis elegans hsd-2 (21% identical). Paralogues in human: SDR42E1 (31% identical), SDR42E2 (27% identical), HSD3B7 (26% identical), HSD3B2 (25% identical), HSD3B1 (24% identical), GALE (20% identical), UXS1 (19% identical), TGDS (17% identical), GMDS (16% identical), GFUS (14% identical).
Diseases named in the same sentence as NSDHL in open-access papers:
NSDHL is named in the same sentence as 25 diseases in open-access papers, as found by Europe PMC text mining. Sharing a sentence is not in itself a finding about the gene and the disease. The quoted sentences say what the papers report.
CHILD syndrome (11 papers, 2009 to 2025). CHILD syndrome (Congenital Hemidysplasia with Ichthyosiform nevus and Limb Defects, CS) is an X-linked dominant genodermatosis characterized by unilateral inflammatory and scaling skin lesions with ipsilateral visceral and limb anomalies. "Here we report the first Sri Lankan patient with CHILD syndrome due to a novel heterozygous variant (NSDHL, c.713C > A, p.Thr238Asn)." (PMID 32819291, 2020). "Loss-of-function variants in the NSDHL gene have been associated with epidermal nevi in humans with congenital hemidysplasia, ichthyosiform nevi, and limb defects (CHILD) syndrome and in companion animals." (PMID 33143176, 2020). "To date, a wide range of variants in the NSDHL gene have been described as suspected causative variants for the pathogenesis of CHILD syndrome in humans." (PMID 33143176, 2020). "Mutations of NSDHL have been related to neurodevelopmental diseases including CHILD syndrome (OMIM: 308050) and CK syndrome (OMIM: 300831)." (PMID 30376821, 2018). "Variants in the NSDHL gene cause CHILD syndrome in humans, and the bare patches (Bpa) and striated (Str) phenotypes in mice." (PMID 28739597, 2017). "The mutational spectrum of NSDHL in CHILD syndrome is broad, and includes missense variants exchanging conserved amino acids in the encoded protein, as well as deletions, insertions or splice site variants and the complete deletion of the gene." (PMID 28739597, 2017). "Mutations in NSDHL are associated with the very rare CHILD syndrome in humans, which is an X-linked dominant disorder of lipid metabolism, as well as the recently described CK syndrome." (PMID 23979938, 2013). "CHILD syndrome, an X-linked dominant trait with lethality for male embryos, can also be traced to mutations in NSDHL, a gene playing crucial roles in the cholesterol biosynthetic pathway." (PMID 19811689, 2009). "Importantly, mutations in the NSDHL gene in humans have been linked to an X-linked dominant condition called CHILD syndrome (‘congenital hemidysplasia with ichthyosiform erythroderma and limb defects’, reviewed in Herman, 2000) that is usually lethal in males." (PMID 32969791, 2020). "Two other patients with ILVEN were found to have mutations in the NAD(P)H steroid dehydrogenase-like protein (NSDHL) gene, changing the diagnosis to CHILD nevus." (PMID 40103681, 2025). "In CHILD syndrome, NSDHL function is presumably eliminated or greatly reduced; CK syndrome affects only males." (PMID 30376821, 2018). "The NSDHL gene encodes the enzyme NAD(P) dependent steroid dehydrogenase-like, which is involved in cholesterol biosynthesis and has been associated with human CHILD syndrome, as well as canine and feline congenital epidermal nevi." (PMID 33143176, 2020). "NSDHL mutations in humans cause CHILD syndrome (congenital hemidysplasia with ichthyosiform erythroderma and limb defects), a rare X-linked dominant disorder with presumed lethality for CHILD causing alleles and, with hypomorphic NSDHL mutations, CK syndrome, a form of X-linked mental retardation." (PMID 21912524, 2011).
breast carcinoma (7 papers, 2021 to 2025). "In the present study, high NSDHL expression was associated with shorter RFS in patients with ER + breast cancer." (PMID 39516821, 2024). "The NAD(P)-dependent steroid dehydrogenase-like (NSDHL) gene, which encodes sterol dehydrogenase or decarboxylase, is also significantly overexpressed in breast cancer and correlates with poor survival outcomes, particularly in triple-negative breast cancer cases." (PMID 40002245, 2025). "This study aimed to elucidate the molecular mechanisms by which NSDHL regulates the capacity of BCSCs in the ER + human breast cancer cell line, MCF-7." (PMID 39516821, 2024). "In this study, we investigated the involvement of NSDHL in the regulation of BCSCs, which are thought to be responsible for ER + breast cancer recurrence." (PMID 39516821, 2024). "NSDHL knockdown suppressed tumor spheroid formation in MCF-7 human breast cancer cells grown on ultralow-attachment plates." (PMID 39516821, 2024). "NAD(P) dependent steroid dehydrogenase-like (NSDHL) is an enzyme involved in cholesterol biosynthesis and is found to promote breast cancer growth and metastasis, as well as serve as a biomarker for early detection of gastric cancer." (PMID 37938654, 2023). "NSDHL knockdown suppresses breast cancer cell proliferation and migration via TGF-βRII endosomal degradation." (PMID 36115986, 2022). "The identification of NSDHL with CLDs in breast cancer cells is consistent with previous observations of its functional association with CLDs and role in metastasis." (PMID 34141606, 2021). "We also showed that the stemness-related transcription factors SOX2 and NANOG, in the context of the TGF-β downstream signaling cascade, are linked to NSDHL, which is consistent with TGF-β-mediated signaling to enrich and maintain the stemness of breast cancer cells." (PMID 39516821, 2024). "In this study, we hypothesized that NSDHL, owing to its significance in ER + breast cancer, is involved in the maintenance and propagation of BCSCs." (PMID 39516821, 2024). "The cholesterol-metabolizing enzyme NSDHL is a potential metastatic driver in breast cancer." (PMID 37333985, 2023). "NSDHL is highly expressed in human breast cancer tissues and predicts a poor prognosis." (PMID 36115986, 2022). "Thus, NSDHL promotes breast cancer proliferation and metastasis through inhibition of TGF-βRII degradation, indicating that cholesterol upregulates TGF-βRII and subsequent TGF-β signaling." (PMID 36115986, 2022). "NSDHL has also been shown to promote breast cancer progression." (PMID 34141606, 2021). "In this study, we found that NSDHL and Dhcr21 were significantly expressed in the expo groups, which had a crucial role in regulating survival, proliferation, cell cycle, migration, and invasion of breast cancer cells and promotion of breast cancer progression and metastasis." (PMID 35200397, 2022). "Thus, the localization of NSDHL to CLDs in MCF10CA1a cells shown in this study suggests that it may promote breast cancer progression by regulating cholesterol synthesis." (PMID 34141606, 2021). "In RNA-sequencing data from The (TCGA) database, a positive correlation between the expression of NSDHL and SOX2 was found in luminal-type breast cancer specimens (n = 998)." (PMID 39516821, 2024). "In a previous study, we first reported NSDHL as a biomarker of poor prognosis to accelerate breast tumor growth and metastasis and to reduce RFS in patients with ER + breast cancer." (PMID 39516821, 2024). "NSDHL is present at higher protein levels in metastatic compared to non-metastatic breast cancer cell lines, and knockdown of NSDHL in metastatic BT-20 and MDA-MB-231 cells reduced cell viability, colony formation, and cell migration." (PMID 34141606, 2021).
breast carcinoma (continued). "Our findings revealed that NSDHL plays an important role in maintaining the BCSC population and tumor-initiating capacity of ER-positive MCF-7 spheroids, suggesting that NSDHL is an attractive therapeutic target for eliminating BCSCs, thus preventing breast cancer initiation and progression." (PMID 39516821, 2024).
CK syndrome (3 papers, 2011 to 2018). "CK syndrome caused by NSDHL mutations is characterized by mild to severe cognitive impairment, seizures beginning in infancy, microcephaly, cerebral cortical malformations and a thin body habitus." (PMID 30376821, 2018).
ichthyosiform erythroderma (3 papers, 2011 to 2020). "Inhibition of cholesterol synthesis possibly due to loss-of-function mutations in the NADP dependent steroid dehydrogenase-like (NSDHL) gene can cause CHILD syndrome (Congenital Hemidysplasia with Ichthyosiform Erythroderma and Limb Defects)." (PMID 32054030, 2020).
breast tumor (2 papers, 2020 to 2024). "NAD(P)-dependent steroid dehydrogenase-like protein (NSDHL), which is involved in breast tumor growth and metastasis, has been implicated in the maintenance of cancer stem cells." (PMID 39516821, 2024). "In this study, we demonstrated that NSDHL knockdown affects the cell cycle, survival, proliferation, and migration of breast cancer cells, resulting in suppression of breast tumor progression and metastasis." (PMID 32366230, 2020). "We observed that NSDHL knockdown suppressed the primary tumor growth as well as lung metastasis in orthotropic breast tumor model injected with NSDHL-knockdown MDA-MB-231 cells." (PMID 32366230, 2020). "Additionally, based on RNA-Seq from the TCGA database, we revealed a significant positive correlation between NSDHL and SOX2 in the luminal breast tumor tissues of patients." (PMID 39516821, 2024).
gastric cancer (2 papers, 2022 to 2025). A primary or metastatic malignant neoplasm involving the stomach. "Xiao Y found that the over expression of NSDHL in gastric cancer (GC) was significantly correlated with local tumor invasion." (PMID 35200397, 2022). "Among them, NSDHL is positively regulated by CPSF1 and promotes the progression of gastric cancer." (PMID 39781570, 2025).
pancreatic cancer (2 papers, 2020 to 2024). "NSDHL is upregulated in highly proliferative cells and inactivation of NSDHL blocks the growth of skin and pancreatic cancer cells." (PMID 32366230, 2020). "Treatment with atorvastatin or NSDHL knockout activates SREBP1, which promotes TGF-β1 expression and induces a canonical Smad2 and Smad3 effector cascade, resulting in the induction of epithelial-mesenchymal transition in pancreatic cancer." (PMID 39516821, 2024).
cholangiocarcinoma (1 paper, 2024). A carcinoma that arises from the intrahepatic biliary tree (intrahepatic cholangiocarcinoma) or from the junction, or adjacent to the junction, of the right and left hepatic ducts (hilar cholangiocarcinoma). "The objective of this work was to examine the NSDHL expression pattern in cholangiocarcinoma and elucidate its role and associated mechanisms in the progression of cholangiocarcinoma." (PMID 39290276, 2024). "This study revealed that 3-hydroxysteroid dehydrogenase (NSDHL) expression was elevated in cholangiocarcinoma." (PMID 39290276, 2024). "In this study, we first compared NSDHL expression in cholangiocarcinoma cells and normal cholangiocytes (HIBEpiCs)." (PMID 39290276, 2024). "However, overexpressing NSDHL in the livers of C57BL/6 mice with fully functional immune systems greatly accelerated the growth of cholangiocarcinoma." (PMID 39290276, 2024). "Immunohistochemical analysis of 46 cholangiocarcinoma tissues confirmed elevated NSDHL expression." (PMID 39290276, 2024). "To determine whether NSDHL promotes the occurrence of cholangiocarcinoma, we altered the expression of NSDHL in various cholangiocarcinoma cell lines." (PMID 39290276, 2024). "However, NSDHL overexpression strongly enhanced the promotion of AKT/YAP-driven cholangiocarcinoma." (PMID 39290276, 2024). "Western blotting analysis of various cholangiocarcinoma cell lines (RBE, HCCC9810, HUCCT1, TFK1, and SNU869) revealed increased NSDHL levels." (PMID 39290276, 2024). "A study revealed an inverse relationship between the expression of NSDHL and the infiltration of NK cells, activated CD4+ T cells, and neutrophils in individuals who were diagnosed with cholangiocarcinoma." (PMID 39290276, 2024). "However, we found that the expression of NSDHL in mouse cholangiocytes promoted the AKT- and YAPS127A-induced development of cholangiocarcinoma, and elevated the number of Ki67-positive cells." (PMID 39290276, 2024). "Additionally, increased expression of NSDHL does not affect the invasive capacity of cholangiocarcinoma cells." (PMID 39290276, 2024). "In addition, high NSDHL expression was correlated with reduced survival in cholangiocarcinoma patients in the GEPIA database, emphasizing its potential role in the progression of cholangiocarcinoma." (PMID 39290276, 2024). "Additionally, NSDHL expression was assessed in six cholangiocarcinoma tissues and their adjacent noncancerous counterparts, and the results revealed increased NSDHL expression in the cancerous tissues." (PMID 39290276, 2024).
Intellectual disability (1 paper, 2018). "The gene encoding NAD(P)H steroid dehydrogenase-like protein (NSDHL) is expressed in developing cortical neurons and glia, and its mutation may result in intellectual disability or congenital hemidysplasia." (PMID 30376821, 2018).
myeloma (1 paper, 2023). "In addition, MDH2, MPC2, PAXIP1, and NSDHL were upregulated in myeloma patients." (PMID 37333985, 2023).
Obesity (1 paper, 2018). Accumulation of substantial excess body fat. "HMGCS1, NSDHL and FDFT1 encode 3-Hydroxy-3-methylglutaryl-CoA synthase, squalene synthase and NAD(P)H sterol dehydrogenase, respectively, which are all key enzymes involved in different steps of cholesterol biosynthesis and some of which are modulated in obesity." (PMID 30068314, 2018).
psoriasis (1 paper, 2023). An autoimmune condition characterized by red, well-delineated plaques with silvery scales that are usually on the extensor surfaces and scalp. "The administration of an ointment containing cholesterol and simvastatin to patients with the NSDHL gene mutation who had psoriasis-like lesions effectively restored the hyperproliferation and inflammatory process." (PMID 37234169, 2023). "Mutations in the MSMO1 gene, which encodes the sterol-C4-methyl oxidase (SMO), and the NSDHL gene can cause psoriasis-like dermatitis, inflammatory cell infiltration, and the accumulation of meiosis-activating sterol (MAS), an intermediate product of cholesterol metabolism, in the skin of patients." (PMID 37234169, 2023).
skin tumor (1 paper, 2020). "NSDHL deficiency abrogates the skin tumor development induced by oncogenic KRASG12D in mice, implicating that it is involved in tumor development." (PMID 32366230, 2020). "Conditional inactivation of NSDHL antagonizes skin tumor proliferation and prevents the development of pancreatic ductal adenocarcinoma in a mouse model." (PMID 32366230, 2020).
triple-negative breast carcinoma (1 paper, 2022). An invasive breast carcinoma which is negative for expression of estrogen receptor (ER), progesterone receptor (PR), and human epidermal growth factor receptor 2 (HER2). "For instance, NSDHL, a crucial enzyme for cholesterol biosynthesis, has been reported to promote metastasis in triple-negative breast cancer." (PMID 35222371, 2022).
xanthoma (1 paper, 2018). A non-neoplastic disorder characterized by a localized collection of histiocytes containing lipid. "A missense mutation in exon 6 of the 3β-hydroxysteroid dehydrogenase (NSDHL) gene that plays an important role in cholesterol biosynthesis was found in 22% of cutaneous xanthomas, but this mutation has not been examined in OVX." (PMID 29924759, 2018).